TLR4 (toll like receptor 4)
Diseases named in the same sentence as TLR4 in open-access papers (continued):
Sharing a sentence is not in itself a finding about the gene and the disease.
Obesity (continued). "By far, at least three major mechanisms have been identified as triggers of obesity-associated metabolic inflammation including endoplasmic reticulum (ER) stress, toll-like receptor 4 (TLR4) activation, and changes in gut microbiota." (PMID 33036205, 2020). "Inflammation has long been known to be a hallmark of obesity, owing to the recruitment of macrophages to adipose depots and the enhancement of TLR-4 signaling by saturated fatty acids." (PMID 33072120, 2020). "Several research papers address the link of TLR4 polymorphism with obesity and MeS, but such kind of studies among Arab subjects is scarce." (PMID 32708841, 2020). "TLR2 and TLR4 contribute to metabolic syndrome associated with HFD-induced obesity, insulin resistance and tissue inflammation." (PMID 32937828, 2020). "The current study explored the impact of TLR4 receptor genotypes rs4986790 and rs4986791 polymorphisms (TLR4D299G/T399) and TLR4 protein expression in obesity and metabolic syndrome components." (PMID 32708841, 2020). "We further analyzed the interaction of TLR4 rs10759932 and rs11536889 polymorphism with obesity, smoking, drinking, hypertension, and dyslipidemia in the risk of AAD." (PMID 33426065, 2020). "It has also been reported that upregulation of TLR4 signal pathway is involved in depression associated with other diseases, such as Alzheimer’s disease, obesity and alcohol addiction." (PMID 31139084, 2019). "In this review, we present an overview of the molecular mechanisms underlying obesity-induced hypothalamic inflammation and insulin resistance with peculiar focus on the role of resistin/TLR4 signaling pathway." (PMID 30906281, 2019). "These contradictory data also highlight that, besides TLR4 signaling, other pathways are critically involved in obesity-associated inflammation and insulin resistance." (PMID 30906281, 2019). "In this regard, our group has recently reported that TNC, through TLR4, is implicated in the etiopathology of obesity adipose tissue inflammation." (PMID 30818874, 2019). "In loss-of-function mouse models, TLR4-deficient mice are protected from diet-induced obesity due to the decrease in proinflammatory cytokine levels." (PMID 31582899, 2019). "Obesity is also associated with elevated levels of free fatty acids (FFAs), which were originally postulated to act as a TLR4 agonist, as TLR4−/− mice are protected from obesity-associated inflammation." (PMID 31249530, 2019). "This review highlights molecular mechanisms underlying obesity associated hypothalamic inflammation and insulin resistance with particular focus on the role of resistin/TLR4 signaling pathway." (PMID 30906281, 2019). "Together, these findings suggest a much broader role for TLR4 in obesity-associated loss of BM integrity than is currently appreciated, with TLR4 regulating not only myeloid potential but also B lymphoid potential and hematopoietic rebound." (PMID 29453396, 2018). "A previous study demonstrated a key role for obesity-associated IL-1 in enhancing BM monocytosis in TLR4-sufficient CMP and GMP11." (PMID 29453396, 2018). "Here, we use adoptive transfer and mixed BM chimera approaches to examine the impact of TLR4 to obesity-associated BM alterations, and begin to prioritize the importance of biologically relevant TLR4 ligands." (PMID 29453396, 2018). "Gut microbiota have been associated with obesity-activating innate immunity through the LPS Toll-like receptor 4 axis." (PMID 30050954, 2018). "Strikingly, LKSneg and CLP subsets from the TLR4-deficient donor partner were protected from the BM myeloid>lymphoid bias in obesity while their WT progenitor counterparts remained susceptible." (PMID 29453396, 2018). "High TLR4 mRNA expression was also associated with obesity (adjusted Odds Ratio (AOR) = 2.03, 95% CI = 1.13–3.63, p = 0.017)." (PMID 30034633, 2018). "Two lines of evidence link obesity-associated immune cell dysregulation with the major innate immune sensor Toll-like receptor 4 (TLR4)." (PMID 29453396, 2018).
Obesity (continued). "The potential role of TLR4 signaling in mediating obesity-induced microglial activation and associated neural impairment is unclear." (PMID 30396359, 2018). "Our findings demonstrate a broader role for TLR4 in obesity-associated BM dysfunction than is presently recognized, and reveal a direct requirement for TLR4 on BM precursors." (PMID 29453396, 2018). "TLR4-deficient mice were recognized as resistant to the inflammatory activation induced by obesity or free fatty acids and protected from insulin resistance." (PMID 28814977, 2017). "Multiple studies have reported that TLR4 deficiency attenuates obesity and insulin resistance in mice." (PMID 29259211, 2017). "This study has identified GSTO1-1 as a novel target for the development of drugs for the treatment of inflammation mediated via TLR4 and possibly the treatment of the inflammation associated with obesity." (PMID 29259211, 2017). "Our data are consistent with the observation that TLR4 deficient mice are also protected from ER stress response in diet-induced obesity." (PMID 28898202, 2017). "This treatment approach, however, failed to eliminate several pathological features associated with MetS, including obesity, hyperglycemia or TLR4-associated endotoxinemia." (PMID 28422962, 2017). "Our results are consistent with studies showing central alterations in TLR4 expression linked to the development of obesity." (PMID 27159520, 2016). "Mice exposed to HFD show peripheral and central alterations in TLR4 expression levels linked to the development of obesity." (PMID 27159520, 2016). "Obesity has been associated with activation of pro-inflammatory pathways in the brain, as a high fat diet up-regulated expression of toll like receptor 4 (TLR4), high-mobility group protein B1 (HMGB1), vascular endothelial growth factor (VEGF) and COX-2." (PMID 27655189, 2016). "In summary our results suggest that in obesity associated hypertension TLR4 SNP rs4986790 cases present a lower SBP, pulse pressure and less hypertension." (PMID 26435700, 2015). "The immunometabolic role of TLR2 and TLR4 makes these receptors and their associated pathways critical for identifying targets to treat metabolic conditions such as obesity-induced inflammation and type-2 diabetes (T2D)." (PMID 26312071, 2015). "As observed in mice models of diet-induced obesity, TLR4 deficiency prevented the enhanced release of TNF-α and IL6 in our hypoxic mice." (PMID 25873766, 2015). "Accordingly, in obesity- and diabetes-associated endothelial dysfunction by increasing oxidative stress TLR4 plays a key role." (PMID 25093580, 2014). "Obesity is strongly associated with the expression of TLR4 (77%, MFI (Mean Fluorescence Index) 7.70) and CD14 (86% MFI 1.61) with 66% double positives (p = 0.000)." (PMID 25493077, 2014). "Previous studies have demonstrated that saturated fatty acids activate TLR4 and that this response is tightly associated with obesity-induced inflammation." (PMID 24281248, 2014). "Loss-of-function mutation in Toll-like receptor 4 prevents diet-induced obesity and insulin resistance." (PMID 25184806, 2014). "TLR4 expression is increased in obesity; when the gene encoding TLR4 was deleted, HFD mice were protected from insulin resistance and weight gain compared to controls." (PMID 23577240, 2013). "C3H/HeJ mice, which have a loss-of-function mutation in TLR-4, were protected against the development of diet-induced obesity and were less susceptible to fat-induced inflammation and insulin resistance." (PMID 23800102, 2013). "Mice deficient in TLR4 are protected from obesity-induced insulin resistance and inflammatory insults." (PMID 24025421, 2013). "TLR4 is directly implicated in diet-induced obesity and atherosclerosis through studies in mouse models, while dietary modulation of the gastrointestinal biome has been shown to influence blood levels of LPS." (PMID 23497455, 2013).
Obesity (continued). "TLR4 deficiency protects from obesity and glucose intolerance induced by a HFD as well as from ER stress in the main organs for glucose and lipid metabolism (skeletal muscle, liver and adipose tissue)." (PMID 23741455, 2013). "TLR-4-deficient 10ScN mice were selectively protected against obesity-induced by diets high in saturated fat." (PMID 23800102, 2013). "It was found that in C3H/HeJ mice a loss-of-function mutation (Pro712His) in TLR4 prevents diet-induced obesity and IR." (PMID 23239997, 2012). "Further, experimental studies in mouse models of TLR4 deficiency demonstrate a reduction in diet induced obesity and atherosclerosis." (PMID 22709547, 2012). "In this context, it would be anticipated that suppression of TLR4 signaling would reduce the deleterious metabolic effects associated with obesity and consumption of high fat diet." (PMID 22253759, 2012). "Observations from these studies suggested that the saturated fat-induced TLR4 signaling pathway is a likely mechanism linking dietary fat with inflammation and insulin resistance associated with obesity and type-2 diabetes." (PMID 21314942, 2011). "Conversely, loss of function of TLR4 led to the protection of saturated fat-induced insulin resistance and diet-induced obesity in mice." (PMID 21314942, 2011). "Conversely, loss of function mutation in TLR4 protected against diet-induced obesity, hyperinsulinemia and inflammation in response to diet high in saturated fat." (PMID 21314942, 2011). "As saturated fatty acids-induced activation of TLR4 is involved in enhancing metabolic disease, MyD88-deficient mice would be expected to attenuate obesity-associated diabetes." (PMID 20824098, 2010). "To evaluate molecular mechanisms linking obesity-associated diabetes down-stream of TLR4, we investigated physiological role of MyD88 in high-fat diet (HFD)-induced obesity." (PMID 20824098, 2010). "A loss-of-function mutation in TLR-4 prevents diet-induced obesity in mice and the development of insulin resistance." (PMID 20508843, 2010). "The association between TLR4 Asp299Gly polymorphism and lung function in relation to obesity (in terms of BMI or waist circumference or other metabolic syndrome components) is an uncharted area." (PMID 19772581, 2009). "Mice deficient in TLR4 or its co-receptor CD14 are protected against diet-induced obesity and insulin resistance." (PMID 19513118, 2009). "Furthermore, high palmitic acid levels are associated with insulin resistance and obesity, potentially promoting neuroinflammation through activation of the toll-like receptor 4 pathway, which, in turn, can impair cognitive function." (PMID 41517237, 2026). "Obesity is a low-grade chronic inflammatory disease, as is nasal polyposis, which has been associated with the A/G genotypes of the SNP A896G and the C/T of the SNP C1196T of the TLR4 gene." (PMID 40552316, 2025). "In addition to peripheral insulin resistance, obesity impairs insulin sensitivity in the hypothalamus, where the central Resistin/TLR4 signaling axis has been implicated in promoting hypothalamic inflammation and systemic metabolic dysfunction." (PMID 41282294, 2025). "Moreover, HFD exposure does not significantly affect GI transit or colonic myenteric cell density in TLR4-deficient mice, underscoring the critical role of TLR4 signaling in enteric neuroinflammation and motility disturbances in diet-induced obesity." (PMID 41226745, 2025). "In summary, this study demonstrated that G-SDF and SDFfbs effectively mitigate the double damage caused by obesity and antibiotic exposure by modulating the LPS/TLR4/MyD88/NF-κB pathway, protecting the intestinal barrier, and restoring the gut microbiota balance." (PMID 40659561, 2025).
Obesity (continued). "HFD did alter ileal 5-HT levels only in WT mice, indicating the presence of low-grade intestinal inflammation and impaired ileal neuromuscular function, further supporting the involvement of TLR4 signaling in obesity-associated small intestine dysmotility, consistent with previous reports." (PMID 41226745, 2025). "Obesity is associated with enteric dysfunctions, including gut dysmotility and neurodegeneration, which may involve Toll-like receptor 4 (TLR4) signaling." (PMID 41226745, 2025). "Human polymorphisms for TLR4 genes have been associated with increased susceptibility to infectious and non-infectious diseases (i.e., inflammatory bowel disease, metabolic syndrome, obesity, T2D, cardiovascular disorder, and cancer)." (PMID 41226745, 2025). "TLR4 has been linked with chronic low-grade inflammation and obesity in aged mice." (PMID 39336586, 2024). "TLR4 knockout prevented bone loss in diabetic rats by inhibiting osteoclast hyperactivity, which might be mediated by the regulation of obesity-associated protein-mediated m6A modification." (PMID 38504994, 2024). "Furthermore, TLR4 is responsible for the production of signal proteins that trigger obesity-associated changes, mainly c-Jun N-terminal kinase (cJNK) and NF-κB." (PMID 39064298, 2024). "A recent study found that n-3 polyunsaturated Fas (PUFA) could alleviate the progression of obesity-associated OA through modulation of the HMGB1-RAGE/TLR4 signaling pathway." (PMID 39744183, 2024). "Inhibition of TLR4 alleviates the symptoms of obesity and diabetes; however, the hypoglycemic and hypolipidemic actions of TLR4 deficiency in mice with obesity and diabetes are unknown." (PMID 38275739, 2024). "However, in the context of obesity and leptin resistance with the activation of the TLR4/Myd88/NFkB axis, an enhanced SOCS3 expression occurs, causing a pathologic leptin signaling inhibition." (PMID 38933275, 2024). "In addition, TLR4-Thr399Ile has been associated with the presence of obesity, a comorbidity commonly found in patients with MASH, thus suggesting its indirect influence on liver disease via broader metabolic and inflammatory pathways." (PMID 39459627, 2024). "Many studies have been conducted to investigate the processes underlying hypothalamus inflammation, such as the Toll-like receptor 4 (TLR-4) pathway (Molecular mechanisms underlying obesity-induced hypothalamic inflammation and insulin resistance: Pivotal role of resistin/tlr4 pathways)." (PMID 37764744, 2023). "The tissue inflammatory state during obesity may be caused by TLR-4/NF-κB pathway activation in macrophages via FFA action, which promotes the synthesis and secretion of proinflammatory cytokines, including IL-6, TNF-α, IL-1β, and IL-18." (PMID 37372966, 2023). "The high expression of CD36, TLR4, and NF-κB p65 in monocytes may be involved in chronic inflammation caused by obesity." (PMID 37403139, 2023). "TLR4 is known to cause obesity-associated insulin resistance." (PMID 37028769, 2023). "The obtained results indicate a potential mechanism of obesity-induced thrombotic complication caused by fatty acid activation of NF-κB signalling and vWF upregulation and help to identify various compensatory mechanisms related to TLR4 signal transduction." (PMID 38203423, 2023). "In this study, we identified four dietary patterns for male children and female children, respectively, to further analyze the association of different dietary patterns with obesity and related indicators, as well as their interaction with TLR4 rs1928295 polymorphisms." (PMID 37571378, 2023). "Nonetheless, the TT genotype of TLR4 rs1928295 locus identified in this study has the potential to serve as a risk factor for predicting overweight/obesity in Chinese Han children aged 7–12 years, providing a new valuable clue for preventive interventions against childhood obesity." (PMID 37571378, 2023).
Obesity (continued). "In addition, two studies found that some TLR4 polymorphism is linked to a higher probability of developing obesity and metabolic disorders, and this is proof that supports the key role of TLR4 in these diseases." (PMID 36674680, 2023). "Studies have shown that n-3 PUFA might play an anti-inflammatory role by attenuating the activation of the TLR4 signaling pathway through saturated fatty acids, thereby reducing the risk of obesity." (PMID 37571378, 2023). "Gut microbiota dysbiosis may contribute to obesity-associated AF by activating ferritinase and TLR4/NF-κB/NLRP3 inflammasome signaling pathways on atrial pathological remodeling." (PMID 38077349, 2023). "Besides, the toll-like receptor 4 (TLR4) pathway performs a crucial function in obesity-associated KOA, a condition believed to be engaged in systemic low-density inflammation." (PMID 35959426, 2022). "Exercise has been shown to reduce TLR4 expression in rats with diet-induced obesity, with both acute and chronic exercise causing a significant suppression in the TLR4 signaling pathway in the muscle, liver, and adipose tissue and improvement of insulin signaling and sensitivity." (PMID 36360622, 2022). "LPS can trigger inflammation through the Toll-like receptor 4 (TLR4) signalling pathway in preeclampsia, hence this could explain why obesity increases the risk of pre-eclampsia." (PMID 35209853, 2022). "In fact, obese adipose tissue is characterized by elevated saturated fatty acids released by obesity-associated lipolysis that induce macrophage activation via toll-like receptor 4 (TLR4) stimulating nuclear factor kappa B (NF-kB) signaling and inflammation in adipose tissues." (PMID 36010901, 2022). "A previous study found that long-term PM2.5 exposure in mice leads to obesity via TLR4/Ikbke, which increased the risk of obesity and metabolic syndrome, and inflammatory activation regulated by TLR2/4 and lung lipid oxidation lead to abnormal metabolic function and obesity." (PMID 35392463, 2022). "In high saturated fat fed mice, TLR4 deficiency protects the mice from obesity." (PMID 35348641, 2022). "Overall, these findings suggest that activation of TLR4 may be a key mechanism underlying the inflammatory state and insulin resistance in obesity and T2DM." (PMID 36066991, 2022). "Moreover, RES alleviated inflammation and minimized bodyweight in KOA mice via the TLR4/NF-kB pathway in a high-fat diet (HFD)-induced obesity-associated KOA mouse model." (PMID 35959426, 2022). "Moreover, the use of knock-out mice or loss of function mutations in either TLR2, TLR4 or MyD88 also confirmed their role in obesity-associated inflammation." (PMID 34083551, 2021). "On the other side, TLR4 pathway dysregulation may also account for obesity-associated inflammation and insulin resistance." (PMID 34327205, 2021). "Interestingly, TLR4 is also associated with cardiometabolic comorbidities such as obesity and hypertension, which are known risk factors for severe COVID with hyperinflammation." (PMID 33557133, 2021). "However, liver substrate proteins of PRSS8 other than TLR4, in this context, remain unclarified, as well as the association between fatty liver or deficient lipid metabolism, brought about by obesity, and PRSS8." (PMID 34361079, 2021). "Furthermore, in the high-fat diet (HFD) animal model, EGCG suppresses Toll-like receptor 4 (TLR4) expression, (firmly associated with induced inflammation in obesity), decreases macrophage infiltration, and also insulin resistance." (PMID 33114725, 2020). "Hepatocyte-specific TLR4 deficient mice are also protected from obesity and insulin resistance." (PMID 31582899, 2019). "A deficiency of TLR4 could protect against obesity-induced M1 polarization and adipose tissue inflammation." (PMID 30863401, 2019).